INSR (insulin receptor)
Diseases named in the same sentence as INSR in open-access papers (continued):
Sharing a sentence is not in itself a finding about the gene and the disease.
breast cancer (continued). "As it interferes with Bax regulation, its role in MCF-7 breast cancer activation quercetin inhibits insulin receptor signalling and therefore impairs the proliferation of breast cancer cells." (PMID 36557789, 2022). "Insulin receptor is a known signaling pathway in breast cancer and it has been suggested that insulin receptor activation results in a kinome signature distinct from IGF-1R and also associated with poor outcome." (PMID 34611148, 2021). "Co-transfection experiments in breast cancer cell lines harboring specific disruptions of either the IGF1R or InsR allowed us to investigate the impact of nuclear InsR on InsR gene expression." (PMID 33918477, 2021). "The insulin/insulin receptor (IR) signaling pathway plays an important role in breast cancer progression by stimulating the RAS/RAF/MAPK kinase/ERK cascade in breast tissues, which results in tumor cell proliferation, survival and migration." (PMID 34384462, 2021). "A significant volume of clinical and epidemiological data provides support to the concept that insulin and the insulin receptor (INSR) have an important role in breast cancer." (PMID 32637033, 2020). "Overexpression of IR (insulin receptor) predicts poor survival in patients with non-small cell lung cancer and breast cancer." (PMID 32156062, 2020). "We also showed that exposing breast cancer cells to the dual IGF1R/InsR inhibitor linsitinib can abrogate IGF‐1R signaling and restore endocrine therapy sensitivity." (PMID 31490549, 2020). "The role of the INSR in the initiation and progression of cancer, in general, and breast cancer in particular, has been a controversial issue for many years." (PMID 32637033, 2020). "This simulation tool allowed us to exploit expression data of breast cancer-derived cell lines with specific disruptions of the INSR or IGF1R genes and their targets in an extended network based on nine KEGG pathways." (PMID 32733384, 2020). "MCF7 breast cancer-derived cells with specific disruption of the INSR or IGF1R were used to study gene expression." (PMID 32733384, 2020). "We here reveal the predictive value of positive p‐IGF‐1R/InsR expression for diminished adjuvant tamoxifen benefit in a large cohort of primary ER+ breast cancer patients." (PMID 31490549, 2020). "Ligand-induced migration was inhibited in cells with silenced IGF1R or INSR, indicating that both receptors are involved in breast cancer cell migration." (PMID 31771180, 2019). "Treatment of MCF-7 human breast cancer cells with estradiol induced transcription of INSR within ten minutes as measured by Gro-seq, suggesting direct effects." (PMID 31795422, 2019). "An earlier study noted that synthetic progestin treatment of the T-47D human breast cancer cell line induced INSR expression by two-fold." (PMID 31795422, 2019). "The availability of MCF7 breast cancer cells with specific abrogation of the INSR or IGF1R allowed us to examine the effects of these pathways on the subcellular distribution and activation of the receptors as well as the downstream effectors." (PMID 31771180, 2019).
breast cancer (continued). "We demonstrated that mTORC1 inhibition with RAD001 (everolimus) induces IGF-1R/InsR/IRS-1/IRS-2-dependent activation of PI3K/AKT signaling in ER+ breast cancer cells and human tumors treated ex vivo." (PMID 29507656, 2018). "In a cell study, nuclear InsR-expression was higher in ERα-depleted breast cancer cells and was able to suppress the IGF1R promotor activity in vitro." (PMID 29234306, 2017). "The cytoplasmic and membrane tumor expression of InsR alone and in combination with IGF1R and phospho-IGF1R/InsR in relation to breast cancer outcome has previously been described in the same patient cohort as used in the present study." (PMID 29234306, 2017). "This is in line with a previous report demonstratinga direct association between InsR overexpression and increasedabundance of hybrid IGF1R/InsR receptors, relative to IGF1R homodimers, in breast cancer specimens." (PMID 28030849, 2017). "The selected pIGF1R/InsR antibody was chosen based on a previous publication evaluating the expression of pIGF1R/InsR in breast cancer tissue with IHC, and the specificity by treating DU145 prostate cancer cells with a IGF1R tyrosine kinase inhibitor." (PMID 28030849, 2017). "There are two isoforms of the insulin receptor, InsR-A and InsR-B, where InsR-A is the predominant isoform in breast cancer." (PMID 28030849, 2017). "The fetal isoform A of the insulin receptor (IR-A) is frequently overexpressed in a variety of malignancies including breast cancer." (PMID 28591735, 2017). "In this study, the expression of IGF1R, InsR and pIGF1R/InsR was evaluated in tumors from 946 primary breast cancer patients in a prospective cohort." (PMID 28030849, 2017). "The prognostic importance of tumor-specific nuclear insulin receptor (InsR) expression in breast cancer is unclear, while membrane and cytoplasmic localization of InsR is better characterized." (PMID 29234306, 2017). "Since OSI-906 is a dual IGF1R/InsR inhibitor and both receptors are potential therapeutic targets in breast cancer it is important to consider the inhibitory contribution of both receptors to OSI-906 effects." (PMID 29207959, 2017). "The combined expression of nuclear InsR and ER was investigated in relation to prognosis in different breast cancer treatment groups." (PMID 29234306, 2017). "Altogether these results demonstrate that INSR signaling in breast carcinoma cells is enhanced in the presence of heparanase and results in accelerated cell proliferation." (PMID 28038446, 2017). "In agreement with clinical observations, in vitro heparanase enzyme augmented INSR signaling / downstream AKT activation in breast carcinoma cell lines, and enhanced insulin-induced growth of breast tumor cells." (PMID 28038446, 2017). "While our findings reveal augmented insulin receptor signaling in the presence of heparanase in breast carcinoma, a limitation of our study is that precise molecular mechanism underlying this phenomenon has not been determined." (PMID 28038446, 2017). "Oestrogen-responsive breast cancer cells express relatively more type I IGF receptor than the insulin receptor." (PMID 26801096, 2016). "In conclusion, Sam68 seems to participate in both leptin and insulin receptor signalling in human breast cancer cells, mediating the trophic effects of these hormones in proliferation and cellular growth." (PMID 27415018, 2016). "Metformin has been shown to decrease AKT activity in breast cancer cells and in glioma stem cells through insulin-receptor signaling, which is another potential mechanism for metformin’s anti-neoplastic activity." (PMID 25867026, 2015). "Here we used a panel of MCF7 human breast cancer cell lines that selectively express either one of the isoforms of the INSR or the IGF1R." (PMID 26187749, 2015). "High ratio of INSR:IGF-1R also conveyed resistance to the IGF-1R mAb cixutumumab in breast cancer cell lines." (PMID 26217584, 2015).
breast cancer (continued). "Our finding that metformin reduced insulin receptor activation in MCF-7 breast cancer cells represents an important activity of this drug in controlling cancer cell proliferation." (PMID 24858012, 2014). "MBS-784807 is a dual IGF-1R/InsR inhibitor that can synergize hormonal agents and has been shown to be a potential breast cancer drug." (PMID 24564956, 2013). "In contrast, RNAi-mediated knockdown or pharmaceutical inhibition of IGF-IR/InsR sensitized breast cancer cells to the AKT inhibitor." (PMID 23844554, 2013). "We examined the effects of AKT inhibition and its compensatory upregulation of insulin-like growth factor (IGF)-I/InsR signaling in ER+ breast cancer cells with acquired resistance to estrogen deprivation." (PMID 23844554, 2013). "We have previously identified IGF-IR/InsR signaling as a mechanism of escape from hormone dependence in ER+ breast cancer." (PMID 23844554, 2013). "Various studies have shown that INSRs are increased in most human breast cancers, and both ligand-dependent malignant transformation and increased cell growth occur in cultured breast cells overexpressing the INSR." (PMID 22701472, 2012). "An array of human breast cancer specimens have been found to harbor high expression of the insulin receptor (IR) subtype A, which is involved in the mitogenic response to insulin, as opposed to IR-B which plays a major role in metabolism." (PMID 22226054, 2012). "For instance, both the IGF-1/insulin receptor families and the C/EBPβ isoforms play important roles in cellular processes that regulate mammary development and breast cancer such as cell cycle control, proliferation, and differentiation." (PMID 21854628, 2011). "Both the IGF-1R and insulin receptor are activated and expressed at elevated levels in breast cancer." (PMID 21854628, 2011). "In cell culture, insulin induces a dose-dependent growth response in breast cancer cell lines acting via the insulin receptor, which has been demonstrated to be almost ubiquitously present in human breast cancer and to have prognostic significance." (PMID 24281091, 2010). "An antibody, αIR3, directed against the IGF receptor, IGF1R, blocked IGF activity and tumour growth in xenograft models of human breast cancer, but the antibody had some agonist activity and cross-reactivity with the insulin receptor." (PMID 19536088, 2009). "INSR is activating PI3K, MAPK, and ERK signaling and has been linked to several tumors including leukemia and PPARG can bind to AP2-ɑ and SP1 and decrease the upregulation effect of AP2-ɑ on INSR in breast cancer." (PMID 41168841, 2025). "Insulin receptor signaling pathways have also been explored for breast cancer treatment." (PMID 37626871, 2023). "The investigation of glucose metabolism and insulin receptor expression could have clinical implications in Estrogen Receptor positive breast cancer patients receiving endocrine treatments." (PMID 37361518, 2023). "Insulin receptor is present in many malignant cells, including breast cancer cells, and insulin may be involved in the growth of these malignancies." (PMID 38091511, 2022). "Finally, we show the potential usefulness of the dual IGF‐1R/InsR inhibitor linsitinib to overcome tamoxifen resistance in IGF‐1R‐driven ER+ breast cancer." (PMID 31490549, 2020).
breast cancer (continued). "Overall, our results confirm that positivity of p‐IGF‐1R/InsR might serve as a marker for better prognosis in ER+ primary breast cancer." (PMID 31490549, 2020). "In addition, small interfering RNA technology was used to specifically down-regulate INSR or IGF1R expression in T47D breast cancer cells." (PMID 31771180, 2019). "Thus, recent studies demonstrate that INSR isoform-A modulates metabolic reprogramming of breast cancer cells in response to both IGF2 and indulin stimulation." (PMID 31771180, 2019). "Based on our preclinical findings, we hypothesized that inhibition of ER decreases IGF-1R/InsR/PI3K/AKT signaling induced by mTORC1 inhibition in ER+ breast cancer." (PMID 29507656, 2018). "On the other way, EGFR signaling pathway could induce expression of insulin receptor substrate in breast cancer cells, which could stimulate IGF pathway." (PMID 27105537, 2016). "First, insulin is a well-known growth factor, which may activate the proliferation of breast cancer cells through its interaction with the insulin receptor or the IGF-1 receptor and through activating the mTOR pathway." (PMID 26537234, 2015). "For example, tumor tissue microarrays show that 87% of primary breast tumors express IGF1R; however, the active phosphorylated form of IGF1R/InsR, as measured by immunohistochemistry (IHC), is only present in roughly 50% of breast cancers where it correlates with poor survival." (PMID 25964777, 2015). "Furthermore, the Yee lab has shown that while IGF1R is reduced in tamoxifen resistant breast cancer cells, InsR is still expressed and able to signal via insulin to promote growth." (PMID 25964777, 2015). "One study used two murine mammary tumour cell lines, both expressing INSR and IGF1R." (PMID 26242987, 2015). "Notably, breast cancer cell membranes have been found to have an average of seven times more INSR and 10 times more IGF receptors than normal breast and other tissues." (PMID 24885964, 2014). "Previous work has shown that protein levels of the total insulin receptor are elevated in breast cancer tissue compared to normal breast tissue and that insulin itself may affect tumor progression by acting through its own receptor." (PMID 22046260, 2011). "The insulin receptor has been related to tumor size, grade, and mortality of breast cancer." (PMID 24281091, 2010). "Over-expression of insulin receptors (IR) has been noted in human breast cancer cells and this may make them more responsive to insulin stimulation." (PMID 22493645, 2009). "In addition, the dual InsR/IGF-IR inhibitor linsitinib can prevent the emergence of breast cancer cells that are resistant to long-term estrogen deprivation or antiestrogen treatment and inhibit growth of established ER+ breast cancer xenografts in ovariectomized mice." (PMID 32493414, 2020). "Moreover, most recent clinical observations revealed that breast carcinoma patients with low IR expression levels had significantly longer progression-free survival and overall survival, while presence of phosphorylated INSR/IGF1R is related to poor survival in all breast cancer subtypes." (PMID 28038446, 2017). "While InsR did not provide any individual prognostic information regarding breast cancer events, there was a significant effect modification of InsR on the association between the combined IGF1R and pIGF1R/InsR markers and event-free survival (Pinteraction = 0.041)." (PMID 28030849, 2017). "Finally, in addition to ER status, breast cancer is a heterogeneous disease with multiple subtypes, which may modify the prognostic importance of nuclear InsR." (PMID 29234306, 2017). "In MCF-7 breast cancer cells, SIRT7 inhibition promotes stress resistance, downregulates insulin receptor (INSR), and modulates insulin-like growth factors (IGFs) pathways affecting cell metabolism and growth." (PMID 35328633, 2022).
breast cancer (continued). "In a HER2-driven mouse model of breast cancer, a stiff ECM induces insulin receptor (IR) recruitment to focal adhesions, thus allowing the formation of IR/integrin complexes and preventing IR lysosomal degradation." (PMID 34131655, 2021). "The insulin receptor and IGF-1 receptor are widely expressed in breast cancer cells and promote cell proliferation mainly via the insulin receptor substrate (IRS)/phosphatidylinositol 3-kinase (PI3K) and Ras/mitogen-activated protein kinase (MAPK) pathways." (PMID 33842335, 2021). "We demonstrate that both INSR and IGF1R exhibit a nuclear localization in breast cancer-derived cells." (PMID 31771180, 2019). "The current results demonstrate that both INSR and IGF1R exhibit a nuclear localization in breast cancer-derived cells." (PMID 31771180, 2019). "In vitro, insulin analogue stimulation increases proliferation of breast cancer cells due to enhanced IGF1R (and INSR) signaling, while exposure to human insulin showed low mitogenic potential." (PMID 29486734, 2018). "The findings from this study suggest that this pIGF1R/InsR antibody may be a clinically relevant marker since the results obtained using this antibody indicated a strong independent association with prognosis among non-endocrine-treated breast cancer patients." (PMID 28030849, 2017). "Previous report of such feedback loop in breast cancer cells showed that AKT inhibition resulted in up regulation of HER2, HER3, IGF-1R and INSR expression and downstream signaling." (PMID 27819360, 2016). "Insulin receptor activation activates the ERK pathway; moreover, metformin was reported to inactivate ERK in breast cancer cells." (PMID 26114294, 2015). "Hence, for breast cancer, INSR/HR:IGF-1R ratio may predict response to mAb against IGF-1R." (PMID 26217584, 2015). "Both IGF-1 and insulin are mitogenic and anti-apoptotic for human breast epithelium and also human breast cancer cells; human breast cancer cells often overexpress IGF-1 receptor and insulin receptor." (PMID 26030767, 2015). "Because XMetS enhanced the binding affinity of the INSR for insulin, we studied the effect of XMetS on insulin-stimulated proliferation of MCF-7 human breast cancer cells." (PMID 24533136, 2014). "For a subset of breast cancer samples our approach indicates a potentially common relatively low activity of PDGFR- and INSR-pathways occurring at different levels within the network hierarchy." (PMID 23760067, 2013). "Genes involved in insulin receptor signaling pathway such as insulin like growth factors (IGF-I and –II) have been found to induce growth of many breast cancer cells." (PMID 20336194, 2010). "Differential splicing of INSR occurs more commonly in human breast cancer than in non-tumor breast tissues, and SCAF1 has been proposed as a cancer prognostic biomarker." (PMID 38951817, 2024). "Given that ErbB contributes to IGF-IR/InsR and ER antagonist resistance, co-targeting ErbB, IGF-IR/InsR, and ER may achieve maximal anti-cancer effect on ER+ breast cancer." (PMID 32493414, 2020). "The involvement of the INSR and IGF1R in breast cancer has been extensively reported." (PMID 32733384, 2020). "Given the vital roles of the INSR and IGF1R signaling pathways in breast cancer, and to gain new insight into potential commonalities and divergences in expression patterns between both receptors and their downstream mediators, we employed the BioNSi bioinformatics tool for network simulation." (PMID 32733384, 2020). "Neither the association between nuclear localization of InsR and patient’s BMI or tumor ER status, nor the prognostic importance of the nuclear InsR have been established among breast cancer patients." (PMID 29234306, 2017). "InsR can translocate to the nucleus and act as a transcription factor, but the role of nuclear expressed InsR in breast cancer prognosis has to our knowledge not been previously investigated." (PMID 29234306, 2017).